PPA1 (inorganic pyrophosphatase 1)
Description:
Catalyzes the hydrolysis of inorganic diphosphate into two phosphate molecules. Has MAP kinase serine/threonine phosphatase activity toward c-Jun N-terminal kinase (JNK) and, in neuronal cells, is involved in the negative regulation of neurite growth via JNK dephosphorylation (By similarity).
Synonyms: PPase; IOPPP; PP; SID6-8061; PP1; HEL-S-66p
Tractability: PROTAC: ubiquitination databases record sites on it; its protein half-life has been measured.
Target class: Enzyme; Hydrolase
Gene: Protein-coding gene on chromosome 10 (70,202,831 to 70,233,911, reverse strand). Ensembl gene ENSG00000180817.
Subcellular location: Cytoplasm
Subcellular location (Human Protein Atlas): Vesicles
Pathways (Reactome):
Metabolism: Pyrophosphate hydrolysis
Metabolism of proteins: Cytosolic tRNA aminoacylation
Gene Ontology:
Molecular function: inorganic diphosphate phosphatase activity; MAP kinase serine/threonine phosphatase activity; magnesium ion binding; pyrophosphatase activity
Biological process: phosphate-containing compound metabolic process
Cellular component: extracellular exosome; cytoplasm; cytosol; mitochondrion
Genetic constraint (gnomAD): Loss-of-function variants: 17 observed, 25.45 expected, observed/expected ratio (o/e) 0.67, 90% interval 0.46 to 1. The upper end of that interval is the gene's LOEUF score, 1, which puts it in group 4 of 6, group 1 being the genes least tolerant of losing a copy. Missense variants: 261 observed, 271.98 expected, observed/expected ratio (o/e) 0.96, 90% interval 0.87 to 1.06. Synonymous variants: 84 observed, 89.49 expected, observed/expected ratio (o/e) 0.94, 90% interval 0.79 to 1.12.
Homologues: Orthologues: macaque PPA1 (99% identical), chimpanzee PPA1 (99% identical), pig PPA1 (95% identical), mouse Ppa1 (94% identical), guinea pig PPA1 (94% identical), rabbit PPA1 (89% identical), dog PPA1 (81% identical), rat Ppa1 (75% identical), zebrafish ppa1b (72% identical), tropical clawed frog ppa2 (70% identical), zebrafish ppa1a (64% identical), Drosophila melanogaster Nurf-38 (55% identical), and 1 more. Paralogues in human: PPA2 (63% identical).
Diseases named in the same sentence as PPA1 in open-access papers:
PPA1 is named in the same sentence as 50 diseases in open-access papers, as found by Europe PMC text mining. Sharing a sentence is not in itself a finding about the gene and the disease. The quoted sentences say what the papers report.
colorectal cancer (7 papers, 2015 to 2025). A primary or metastatic malignant neoplasm that affects the colon or rectum. "Simultaneously, analysis of bulk-RNAseq data from the TCGA and GTEx databases revealed significantly higher PPA1 expression in colorectal cancer (CRC) tissues compared to normal colon tissues." (PMID 41315223, 2025). "Some reports showed that PPA1 was differentially expressed in various types of cancers, including enhanced expression in lung adenocarcinoma 4, primary colorectal cancer 3, prostate cancer 13, ovarian cancer 5, and gastric cancer." (PMID 27666431, 2016). "The expression of PPA1 is significantly increased in the metastatic lymph nodes of malignancies, including gastric cancer, colorectal cancer, ovarian cancer, and laryngeal squamous cell carcinoma (LSCC) as assessed by immunohistochemistry or tissue microarrays, compared to that in controls." (PMID 36505776, 2022). "Polypeptide PPA1 was reported to show the potential of targeting PD-L1 in colorectal cancer cell." (PMID 34858817, 2021). "In humans, cytosolic inorganic pyrophosphatase (PPA1) was found to be overexpressed in many types of cancer such as, breast cancer, lung cancer, ovarian cancer, hepatocarcinoma and primary colorectal cancer." (PMID 25923237, 2015).
gastric cancer (7 papers, 2015 to 2025). A primary or metastatic malignant neoplasm involving the stomach. "Inorganic pyrophosphatase 1(PPA1), an essential metabolic enzyme, is overexpressed in lung adenocarcinoma, invasive ductal carcinoma, prostate cancer, gastric cancer, hepatocellular carcinoma, diffuse large B-cell lymphoma, ovarian cancer, and CRC." (PMID 41315223, 2025). "PPA1 over-expression in gastric cancer cell lines promotes its proliferation and increases its aggressiveness." (PMID 36505776, 2022). "More prominently, the expression of PPA1 is significantly higher in patients with advanced gastric cancer and in those with a poorer prognosis." (PMID 36505776, 2022). "In gastric cancer cells, PPA1 plays a role in migration and invasion and in ovarian cancer cells silencing of PPA1 inhibits the proliferation." (PMID 25923237, 2015). "Their findings indicate that PPA1 might be a useful marker for gastric cancer metastasis and progression." (PMID 29100310, 2017). "In humans, the expression of inorganic pyrophosphatase (PPA1) is deregulated in different types of cancer and is involved in the migration and invasion of gastric cancer cells and proliferation of ovarian cancer cells." (PMID 25923237, 2015).
ovarian carcinoma (7 papers, 2015 to 2025). A malignant neoplasm originating from the surface ovarian epithelium. "They showed that PPA1 knockdown reduced the invasiveness and migration of ovarian cancer cells, and PPA1 expression was associated with EMT process." (PMID 36505776, 2022). "In lung cancer, PPA1 expression was associated with tumor size, patients’ age, and smoking status, whereas in ovarian cancer, PPA1 expression was associated with pathological grade (P < 0.05)." (PMID 27666431, 2016). "PPA1 also promotes the aggressiveness of tumor cells in ovarian cancer, and a positive correlation between β-catenin and PPA1 expression has been demonstrated." (PMID 36505776, 2022). "The use of GSK-3β inhibitors blocks the process by which PPA1 promotes β-catenin nuclear translocation, implying that PPA1 promotes EMT in ovarian cancer by participating in β-catenin dephosphorylation." (PMID 36505776, 2022). "To investigate this relationship, we first examined PPA1 expression in human epithelial ovarian cancer (EOC) samples, and found that PPA1 was overexpressed in tumors from EOC patients." (PMID 29100310, 2017). "Based on several results, high PPA1 expression can promote the occurrence and development of ovarian cancer, and PPA1 expression is positively correlated to a poor prognosis for ovarian cancer." (PMID 29100310, 2017). "Our results indicated that PPA1 expression was significantly up‐regulated in various tumor types, especially in lung and ovarian cancer." (PMID 27666431, 2016). "As the bioinformatic analysis of PPA1 supported our IHC results, we further investigated the role of PPA1 in lung and ovarian cancers via an examination of the relationship between PPA1 expression and the clinicopathologic features of each cancer type." (PMID 27666431, 2016). "Collectively, these results supported the notion that PPA1 inhibits proliferation among lung and ovarian cancer." (PMID 27666431, 2016). "Among the 12 types of tumors, PPA1 expression was significantly higher in lung and ovarian cancers (P < 0.001)." (PMID 27666431, 2016). "To investigate the clinical significance of PPA1 in ovarian cancer and lung cancer and to verify our IHC results, we compared PPA1 expression between normal tissue and primary tumor tissue using GEO datasets and bioinformatic analysis." (PMID 27666431, 2016). "We also found that PPA1 expression was increased in the primary tumors of ovarian cancer patients compared with normal ovarian tissue in GSE43346 (P = 0.006) and GSE38666 (P = 0.005)." (PMID 27666431, 2016). "QPCR and western blot examined PPA1 expression in tumor‐derived cell lines including those derived from liver, breast, lung, and ovarian cancers." (PMID 27666431, 2016). "PPA1 was upregulated in neoplasms such as colorectal cancer, lung adenocarcinoma, prostate cancer, hepatocellular carcinoma, breast cancer, and ovarian cancer." (PMID 29100310, 2017). "In conclusion, PPA1 expression was up‐regulated in various types of tumors compared with normal tissues, especially in lung and ovarian cancer, and was found to be involved in the increase in proliferation and the suppression of apoptosis in ovarian and lung cancer cells in vitro." (PMID 27666431, 2016). "Taken together, PPA1 might be useful as an important predictive and prognostic factor in patients with lung and ovarian cancers." (PMID 27666431, 2016). "Based on these results, PPA1 might be useful as an important predictive and prognostic factor in lung and ovarian cancers." (PMID 27666431, 2016). "Together, this data demonstrated that PPA1 is increased in lung and ovarian cancer cell lines." (PMID 27666431, 2016).
ovarian carcinoma (continued). "In ovarian cancer, tumors of histological grades II (n = 12) and III (n = 23) revealed increased PPA1 expression compared with tumors of histological grade I (n = 7)." (PMID 27666431, 2016). "Furthermore, microRNA (miR-545-3p) can target PPA1 to inhibit cell proliferation and invasion and enhance cisplatin resistance by increasing JNK phosphorylation in ovarian cancer." (PMID 36505776, 2022). "At the same time, we detected PPA1 expression in various cell lines, and found that PPA1 expression was higher in lung and ovarian cancer cell lines than in corresponding nontumor cell lines, which were in agreement with the immunohistochemistry results." (PMID 27666431, 2016). "In this study, we stained 675 cases of paraffin‐embedded carcinoma tissues, 305 cases nontumor tissues, and 20 cell lines to determine whether PPA1 is up‐regulated in a variety of tumors, especially in lung cancer and ovarian cancer." (PMID 27666431, 2016). "Moreover, we found that PPA1 expression was up‐regulated in lung and ovarian cancer cell lines compared with nontumor cells." (PMID 27666431, 2016). "The results showed that PPA1 is highly overexpressed in all of the lung cancer and ovarian cancer cell lines compared with both of their corresponding noncancerous cell lines (MRC5, IOSE80), while these same results were not obtained in the hepatoma and breast cancer cell lines." (PMID 27666431, 2016).
breast carcinoma (6 papers, 2015 to 2024). "To further investigate the mechanism underlying the regulatory effects of PPA1 on breast cancer progression and EMT, we first performed western blot and the results demonstrated that silencing PPA1 restrained the phosphorylation levels of PI3K, AKT, and GSK3β." (PMID 34595179, 2021). "Most importantly, we revealed the underlying mechanism that PPA1 regulated breast cancer progression and EMT through the PI3K/AKT/GSK3β pathway." (PMID 34595179, 2021). "Taken together, these results indicate that PPA1 may play a vital role in breast cancer development, and that it may be a diagnostic marker for tumor progression." (PMID 34595179, 2021). "Furthermore, we analyzed the correlation between the expression of PPA1 and patient overall survival (OS), and found that high PPA1 expression was associated with poor clinical outcomes in patients with breast cancer." (PMID 34595179, 2021). "Our results demonstrated that PPA1 was overexpressed in breast cancer and its expression was significantly correlates with clinical progression." (PMID 34595179, 2021). "Collectively, these findings indicated that PPA1 facilitated breast cancer progression and EMT via activating PI3K/AKT/GSK3β signaling pathway." (PMID 34595179, 2021). "In this study, we found that PPA1 was highly expressed in breast cancer compared to its levels in normal breast tissue and that it was correlated with breast cancer clinicopathological characteristics, as well as poor survival in breast cancer patients." (PMID 34595179, 2021). "In our study, we identified that PPA1 promoted breast cancer metastasis via Slug-mediated EMT, proceeding through the PI3K/AKT/GSK3β signaling pathway." (PMID 34595179, 2021). "Taken together, these findings provide novel insight into how PPA1 regulates tumor metastasis, suggesting its potential as a therapeutic target in breast cancer." (PMID 34595179, 2021). "Taken together, these results confirmed that inhibitors targeted PPA1 mediated signaling pathway suppressed breast cancer progression and EMT in vitro." (PMID 34595179, 2021). "Our study demonstrated that PPA1 plays an important role in breast cancer progression for the first time and we extensively explored its functions in vitro and in vivo." (PMID 34595179, 2021). "Consistently, wound healing and transwell assay confirmed that ectopic PPA1 facilitated breast cancer cell migration and invasion." (PMID 34595179, 2021). "Meanwhile, cell-based and mouse models studies indicated that PPA1 promoted proliferation, migration, and invasion of breast cancer." (PMID 34595179, 2021). "In this study, we determined the function of PPA1 in breast cancer and identified the potential molecular mechanism." (PMID 34595179, 2021). "Taken together, these findings verified that PPA1 promoted proliferation, migration, and invasion of breast cancer cells." (PMID 34595179, 2021). "Silencing PPA1 restrained breast cancer proliferation and metastasis by regulating Slug-mediated epithelial-mesenchymal transition (EMT)." (PMID 34595179, 2021). "PPA1 promotes proliferation, migration, and invasion of breast cancer through the PI3K/AKT/GSK3β pathway." (PMID 34595179, 2021). "In order to verify the clinical significance of PPA1 in breast cancer, we first examined PPA1 expression in tissue microarray containing human normal/para-carcinoma breast tissues and breast tumors with different TNM stage and histological grade by IHC." (PMID 34595179, 2021). "To evaluate the function of PPA1 in breast cancer progression in vivo, we performed xenograft experiments using MDA-MB-231 cells." (PMID 34595179, 2021). "To elucidate the function of PPA1 in breast cancer, we first silencing PPA1 in T47D cells by stable expression of control or two PPA1-targeting shRNAs." (PMID 34595179, 2021).
breast carcinoma (continued). "In summary, our results verify that PPA1 can act as an activator of PI3K/AKT/GSK3β/Slug-mediated breast cancer progression and that it is a potential therapeutic target for the inhibition of tumor progression." (PMID 34595179, 2021). "To gain insights into the importance of PPA1 mediated signaling pathway in promoting the breast cancer progression and EMT, we investigated the effects of PI3K inhibitor (LY294002) in MDA-MB-231-PPA1 cells." (PMID 34595179, 2021). "We found that PPA1 was significantly upregulated in the tissues of patients with breast cancer, and its expression was correlated with clinicopathological characteristics." (PMID 34595179, 2021). "Taken together, we confirmed that PPA1 promoted breast cancer proliferation, migration, and invasion through PI3K/AKT/GSK3β signaling." (PMID 34595179, 2021). "In conclusion, we verify that PPA1 is highly expressed in breast cancer and that it is correlated with clinicopathological characteristics." (PMID 34595179, 2021). "Consistent with our results, Mishra DR and his coworkers have proved that PPA1-shRNA can significantly decrease the colony forming ability of breast cancer cells, which suggest that PPA1 can up-regulate cancer cell proliferation and colony formation." (PMID 28938583, 2017). "Recently, PPA1 was found to be overexpressed in several types of malignancies by proteomic studies, including hepatocarcinoma, ovarian cancer, breast cancer and lung cancer." (PMID 28938583, 2017). "In the present study, we have identified and studied the functional promoter region of the PPA1 gene using MCF7 cell line (the human breast cancer cell line) as a model." (PMID 25923237, 2015). "However, the PI3K inhibitor reversed the expression levels of EMT markers and modulated the activation of PI3K/AKT/GSK3β pathway, demonstrating that inhibitors targeted PPA1 mediated signaling pathways suppressed breast cancer progression." (PMID 34595179, 2021). "Moreover, PI3K inhibitors suppress the signaling pathways mediating the effects of PPA1 on breast cancer, resulting in tumor growth and metastasis suppression in vitro and in vivo." (PMID 34595179, 2021). "Moreover, the increased expression of PPA1 was also observed in breast cancer cell lines compared to that in the normal breast cell line." (PMID 34595179, 2021). "Finally, we investigated the mechanism of action of PPA1 in breast cancer progression." (PMID 34595179, 2021). "Thus, PPA1 may serve as a potential marker for evaluating breast cancer progression, and targeting PPA1 may be an attractive therapeutic strategy in breast cancer to prevent tumor metastasis." (PMID 34595179, 2021). "However, the significance of PPA1 expression and its role in breast cancer remains unclear." (PMID 34595179, 2021). "We found that PPA1 expression was positively correlated with TNM stage and histological grade of human breast cancer." (PMID 34595179, 2021). "However, the role of PPA1 in breast cancer progression remains unclear." (PMID 34595179, 2021). "In summary, our study demonstrated a critical role of PPA1 in mediating PI3K/AKT/GSK3β signaling-induced tumor progression, which could be a useful target to prevent breast cancer." (PMID 34595179, 2021).